IL4 (interleukin 4)
Diseases named in the same sentence as IL4 in open-access papers (continued):
Sharing a sentence is not in itself a finding about the gene and the disease.
food allergy (continued). "Our data revealed that values of IL-4 and IL-13 are higher in infants with non-IgE-mediated food allergies, whereas IL-5 and IL-10 are lower, as observed in IgE-mediated food allergies." (PMID 35458127, 2022). "In addition to IL4 and IL17, IgE-mediated intestinal pathological changes in food allergy are driven by IL-9." (PMID 36364962, 2022). "OVA-sensitized mice were protected from food allergy anaphylactic death by 60% and observed with significantly suppression of OVA-specific IgE,IL-17, TH2 cytokines (IL-4, IL-5, IL-10, IL-13) and TH1 cytokines (IFN-γ and IL-12) with the treatment of 25 mg/kg of extract." (PMID 31275149, 2019). "Furthermore, these findings represent a new conceptual paradigm by linking atopic status (IL-4), dietary antigen and IgE/FcεR complex interactions, and inflammatory cues (exemplified by IL-33) with MMC9 biology and food allergy." (PMID 27853507, 2016). "Consistent with this, a reactive increase of mucus production is expected during food allergy model, which is reduced in the absence of IL-4 and IgE." (PMID 22162714, 2012). "In this mouse model of food allergy, we demonstrated a decreased response to a muscarinic agonist, and increased levels of proinflammatory IL-6 and Th2-related IL-4, but not Th1-related IFN-γ mRNAs in jejunum." (PMID 19450258, 2009). "Importantly, serum IL-4, but not IL-13, concentrations were significantly higher in patients with food allergy and S. aureus colonization than in those with S. aureus colonization but no food allergy." (PMID 41005294, 2025). "Overall, our data indicate that the increase in Il4 expression in food allergy primed TFR cells is not due to enhanced Th2 polarization and may be explained by increased activity from AP-1 and Maf transcription factors." (PMID 39377224, 2024). "Notably, the food allergy TFH and TFR cells showed very similar patterns of Il4-regulating transcription factor gene expression, indicating parallel modes of IL-4 gene regulation." (PMID 39377224, 2024). "Moreover, IL-4 has been shown to not only enhance IL-3- or SCF-dependent mast cell proliferation, but also to directly stimulate proliferation via STAT6 in a mouse mode of food allergies." (PMID 35159139, 2022). "The 6 dogs with confirmed CE and IL-4:IL-10 above the 95% CI of the mean of the non-GI group had a cytokine profile that may suggest a GI food allergy based on the studies performed in human and mouse models of GI food allergy." (PMID 31164117, 2019). "Previously, we found that naïve cord blood CD4+ T cells differentiated toward an IL-4-expressing phenotype when activated in the presence of TGF-β and monocyte-derived inflammatory cytokines, the latter are more highly secreted by infants who developed food allergy." (PMID 29922282, 2018). "Regardless, independent of the IL-4 conditions throughout the experimental period, on day 28 of the EW diet, the hyporesponsiveness of T cells and induction of aiTregs were similar between our tolerance (D10) and food allergy (OVA23-3) models." (PMID 28234975, 2017). "Although increased production of IgE and Th2 cytokines (IL-4, IL-5 and IL-13) are considered common markers of food allergy, absence of IgE or increased levels of Th1 cytokines (IL-2, IFN-γ and TNF-α) have also been observed in several instances of food allergy, mainly in response to cow's milk." (PMID 21211037, 2011). "Lack of IL-4 has been recently reported to modulate gut mucosal response in food allergy through diminished expression of TNF-α mRNA, increased Th1 IFN-γ, IL-12p40 regulatory cytokines, thus demonstrating their relevance in the control of allergic inflammatory processes, especially in the intestine." (PMID 20184725, 2010). "Thus, unlike IgG1, IgE is extremely sensitive to IL-4 levels in this food allergy model." (PMID 39377224, 2024).
food allergy (continued). "It is worth noting that the IL-4 in subjects with food allergies is primarily derived from CD4+ T cells rather than ILC2s, and IL-4 released by ILC2s has no discernible effect on food allergies." (PMID 34177881, 2021). "The results showed that the antigen-specific IgE, but not IgG4, IL-4, IFN-γ, IL-17 and TNF-α were detected in all the IBD patients with food allergy." (PMID 27499766, 2016). "Interestingly, increased numbers of duodenal IL-4+ cells, but decreased numbers of IFN-γ+ cells, have also been found in mucosal biopsies from the small intestine of patients with non-IgE-mediated food allergy." (PMID 19450258, 2009).
nasal polyps (85 papers, 2009 to 2026). "These environments are common during the formation of nasal polyps associated with aspirin intolerance, which is also marked by an increase in inflammatory mediators, especially IL-4, IL-5, and IL-13." (PMID 36721412, 2023). "included 106 individuals with CRS (61 with nasal polyps) and found that the T/T allele at position -590 of the IL-4 gene conferred protection against CRS with nasal polyps." (PMID 36419128, 2022). "IL-4 has been associated with type 2 immune mechanism in nasal polyps, and suggested to be a reason for a change in epithelial permeability in nasal polyps." (PMID 34208325, 2021). "In our research, we found that IL-4 VNTR polymorphisms were significantly associated with nasal polyps in the Turkish population (P = 0.036)." (PMID 31650822, 2019). "The present research is the first study to evaluate the role of IL-1RN, IL-2, and IL-4 gene polymorphisms in a Turkish population with nasal polyposis." (PMID 31650822, 2019). "In nasal polyp tissues, IL-4 levels are increased and cause the Th0 cells to transform into Th2 cells." (PMID 23737902, 2013). "Indeed, at the level of upper airways IL-4 and IL-13 play a key role in both inflammatory and structural changes (tissue remodelling) that underlie the formation of nasal polyps." (PMID 37063895, 2023). "Polymorphisms in IL4 have also been associated with chronic rhinosinusitis and nasal polyposis." (PMID 35456412, 2022). "Nasal polyps are benign lobular-shaped growths that project in the nasal cavities; they originate from inflammation in the paranasal mucous membrane and are associated with a high expression of interleukins (IL)-4, IL-5, IL-13, and IgE." (PMID 33287173, 2020). "IL-4 promoter polymorphisms are also associated with nasal polyps in aspirin-sensitive patients." (PMID 22829846, 2012). "Dupilumab, targeting the IL-4 and IL-13 pathways, has demonstrated consistent benefits in reducing nasal polyp scores, improving olfaction, and delaying the need for revision surgery." (PMID 41011011, 2025). "Among the type 2 biologics used for the treatment of nasal polyps, dupilumab (Dupi, anti‐IL‐4) exhibited superior efficacy and safety in indirect comparison studies." (PMID 38974604, 2024). "Our study demonstrated that dupilumab, a monoclonal antibody targeting IL-4 and IL-13 signaling, was highly effective in improving the clinical outcomes of patients with chronic rhinosinusitis with nasal polyps (CRSwNP)." (PMID 39768876, 2024). "Nasal polyps with eosinophils infiltration are accompanied by type-2 inflammation expressing IL-4, IL-5, and IL-13 and high levels of circulatory but particularly local IgE." (PMID 37674852, 2023). "Staphylococcus aureus superantigens contribute to the polarization of type-2 immune response in nasal polyp tissue characterized by Th2 cytokines (IL-4, IL-5, IL-13) production and promote eosinophils infiltration." (PMID 37674852, 2023). "Within such an airway context, type 2 asthma and nasal polyposis develop as a consequence of the overexpression of IL-4, IL-13, and IL-5." (PMID 37240477, 2023). "Several works have reported that Dupilumab (an anti-IL-4/IL-13 biologic drug) effectively reduced the size of nasal polyps and improved the important parameters of disease burden in a number of patients." (PMID 37623491, 2023). "Airway remodeling elicited by IL-4 and IL-13 also occurs via their stimulatory action on M2-type macrophages, which promote fibrin deposition and nasal polyp formation by inhibiting fibrin degradation." (PMID 37240477, 2023). "It has been demonstrated that Dupilumab (an anti IL-4/IL-13 biologic drug) is effective in reducing the size of nasal polyps and in improving patients’ symptoms and thus, quality of life." (PMID 37623491, 2023). "The treatment paradigm for nasal polyposis, previously managed with surgery and topical corticosteroids, has been revolutionized by inhibition of IL-4 and IL-13." (PMID 35608904, 2022).
nasal polyps (continued). "In our data, mast cells were distinguished by their expression of IL4 and IL13, which we also recently observed in a study of human nasal polyposis, a type 2 inflammatory disease associated with far-reaching epithelial remodeling." (PMID 35483355, 2022). "CRSwNP endotype markers with nasal polyposis indicate the desirability of using biological medicines targeting these receptors (IgE, IL-4, IL-5, and IL-13), especially in the treatment of CRS with nasal polyps and asthma (IL-5)." (PMID 35740420, 2022). "Ki-67 correlations with cytokines characterized previously established IL-4, IL-7, and IL-12 involvement in tissue proliferation in primary nasal polyps." (PMID 36285981, 2022). "To further analyze the effects of OSM and IL-4 on nasal-polyp-derived fibroblasts at the cell signaling level, we studied their potential impact on Smad3 nuclear translocation induced by TGF-β1." (PMID 35682987, 2022). "IL-1α, IL-4, IL-6, IL-8, IL-10, IL-12 (p < 0.001), and Ki-67 (p = 0.001) were decreased in the epithelium of the nasal polyp samples in comparison to the control samples." (PMID 36285981, 2022). "IL-4 along with IL-13 is one of the main cytokines driving type 2 inflammation in as much as 80% of patients with nasal polyps." (PMID 36285981, 2022). "IL-1α, IL-6, IL-8, IL-10, IL-12 (p < 0.001), and IL-4 (p = 0.038) were increased in the subepithelial connective tissue of the nasal polyp samples when compared to the control samples." (PMID 36285981, 2022). "In this study, we found that IL-5, IL-13, ECP, and eotaxin levels were significantly increased in the nasal polyps of patients with eCRSwNP or noeCRSwNP, whereas IL-4 levels were only increased in patients with eCRSwNP." (PMID 35747690, 2022). "When comparing nasal polyp samples with normal mucosa from control patients, it was apparent that IL-1α, IL-4, IL-6, IL-7, IL-8, IL-10, IL-12 positive structures were significantly decreased in epithelium of the polyps." (PMID 34208325, 2021). "In nasal polyp samples there were few to moderate IL-4 positive epitheliocytes, but moderate positive structures were seen in connective tissue." (PMID 34208325, 2021). "IL-4 has been observed in many CRSwNP-related studies and has been found to have a high concentration in tissue samples with nasal polyps." (PMID 34208325, 2021). "IL-4 showed a decrease of positive cells in epithelium of nasal polyp patients and an increase in subepithelial connective tissue." (PMID 34208325, 2021). "This suggests a mechanism through which TLR ligands and IL-4 contribute to eosinophilic infiltrates of nasal polyps." (PMID 35008843, 2021). "When evaluating the concentration of interleukins in the eosinophilic nasal polyp cell culture supernatant, a significant decrease in IL-4 concentration (p = 0.0078) was observed, when compared to controls 24 h after exposure of cultures to IFN-α action." (PMID 31870738, 2021). "IL-4 positive structures in nasal polyps were significantly decreased in epithelium (p < 0.001) and increased in the connective tissue (p = 0.014) in comparison to control samples." (PMID 34208325, 2021). "The target proteins, interleukin (IL)-4, IL-5, IL-13, and IgE were previously identified as key mediators in studies using nasal polyp tissues to measure and to interact in ex-vivo settings." (PMID 31452831, 2019). "IL-1 and IL-4 seem to play an important role in the pathogenesis of nasal polyposis because they activate and mobilize eosinophils and stimulate the differentiation and growth of B lymphocytes." (PMID 31650822, 2019). "It was shown only recently that upregulation of IL-4 occurs in nasal polyps, whereas IFN-γ expression is reduced, and that IFN-γ levels do not differ significantly between nasal polyps and control tissue." (PMID 29564208, 2018).
nasal polyps (continued). "Nasal polyps from patients with CRS have elevated levels of CysLTs, IL-33, TSLP, and IL-4 and multiple groups have shown that ILC2s are enriched in nasal polyps, especially eosinophilic polyps, compared to control tissue." (PMID 28959799, 2017). "Anti-IL-4 treatment has been reported effective in reducing nasal polyp burden in CRS patients with nasal polyps." (PMID 28199345, 2017). "An analysis of the expression level indicates the participation of POSTN and IL-4 in the development of chronic rhinosinusitis with nasal polyps in patients with atopy." (PMID 25573836, 2015). "When applying a univariate correlation analysis, only IL-4 correlated significantly between nasal polyp and bronchial biopsies; however, this was due to three outliers." (PMID 26132710, 2015). "Nasal polyp tissues showed significantly (P ≤ 0.01) altered gene expression values for over 4,000 genes and a significant increase of Th2 cytokines (IL-4, IL-5, IL-10, and IL-13) compared to the inferior turbinate (data not shown)." (PMID 24995349, 2014). "The infiltration of inflammatory cells, particularly eosinophils (EOSs) and T lymphocytes, and abnormalities in the cytokines, including the upregulation of interleukin (IL)-4, IL-5 and IL-10, are characteristics of the immune dysfunction of nasal polyps." (PMID 23737902, 2013). "For example, several investigators have proposed that IFN-γ, IL-4, and IL-5-producing lymphocytes are found in nasal polyps, and that nasal polyps possess a mixed pattern of Th1/Th2 cytokines." (PMID 19250527, 2009). "The ERS/ATS group also noted that dupilumab may benefit patients with comorbid severe nasal polyposis, an IL-4/IL-13-driven condition." (PMID 40843371, 2025). "IL-4, whose receptor is directly inhibited by dupilumab itself, plays a key role in Th2 differentiation of lymphocytes and IgE production, and it has been shown to be further increased in atopic patients with nasal polyposis compared to non atopic ones." (PMID 38850424, 2024). "Hence, IL-4 and IL-13 contribute remarkably to the massive eosinophil infiltration which often characterizes asthmatic bronchial walls, as well as the nasal polyps of patients with either CRSwNP or AERD." (PMID 37240477, 2023). "IL-4, IL-7, IL-10, and IL-12 correlate with Ki-67 which suggests the possible involvement of these cytokines in tissue cell proliferation in the case of recurrent nasal polyps." (PMID 36285981, 2022). "Chronic rhinosinusitis with nasal polyps (CRSwNP) is associated with inflammation and tissue remodeling including myofibroblasts differentiation and extracellular matrix (ECM) deposition mediated by TGF-β1 and IL-4." (PMID 35682987, 2022). "Dupilumab, which binds the alpha subunit of IL-4 receptors (IL-4Rα type 1 and type 2), thus inhibiting the signaling of IL-4 and IL-13 acting on the IL-4 and IL-13 receptors, can block type 2 inflammation, leading to a significant improvement of both nasal polyps and other T2-related comorbidities." (PMID 36294873, 2022). "IL-4 messenger ribonucleic acid (mRNA) and protein are overexpressed in nasal polyps." (PMID 35008843, 2021). "Therefore, our aim is to investigate the complex appearance, relative distribution and interlinks of IL-1, IL-4, IL-6, IL-7, IL-8, IL-10, IL-12 and Ki 67 in chronic rhinosinusitis with nasal polyps (CRSwNP) affected human nasal mucosa." (PMID 34208325, 2021). "Our results indicates that anti‐IL‐4/IL‐13 treatment might have utility for controlling the remodeling process within nasal polyps, which has been confirmed to effectively treat severe CRSwNPs." (PMID 34504680, 2021). "The increased IL-4 level in nasal polyposis has been reported in several studies." (PMID 31650822, 2019). "The studies revealed an increased level of POSTN, IL-4 gene expression and a decreased level of COX-2 gene expression that may be associated with the development of chronic rhinosinusitis with nasal polyps." (PMID 25573836, 2015).